SCN1A (sodium voltage-gated channel alpha subunit 1)
Diseases named in the same sentence as SCN1A in open-access papers (continued):
Sharing a sentence is not in itself a finding about the gene and the disease.
neurological disorders (19 papers, 2013 to 2025). "Loss-, gain-of-function and mixed variants in SCN1A (Nav1.1 voltage-gated sodium channel) have been associated with a spectrum of neurologic disorders with different severity and drug-responsiveness." (PMID 39200163, 2024). "The presence of the heterozygous c.1403G>A, p.Arg468Gln CACNB4 variant has been proposed to create more neurological disorders in those patients having a pathogenic SCN1A mutation where the current densities increased in calcium channel." (PMID 35813387, 2022). "Among these, the genes most frequently associated with inherited forms of neurological disorders encode for brain Na+ channels Nav1.1 (SCN1A) and Nav1.2 (SCN2A)." (PMID 26236192, 2015). "In the present study, IPA-identified pathways reveal that the gene encoding sodium channel scn1a, which is a member of the neurological disease functional gene cluster, is up-regulated in the SNI group." (PMID 23597049, 2013). "SCN1A variants are associated with a spectrum of neurologic disorders with variable phenotypes." (PMID 39200163, 2024). "Mutations in SCN1A can result in LOF, GOF, or mixed functional effects and have been linked to a broad spectrum of neurological disorders with highly variable clinical features and treatment responses." (PMID 41515912, 2025). "Recently, de novo mutations in SCN1A have been associated with ASD, and a report of a recognized mutation in SCN1A suggests a wide phenotypic variation of the gene mutations causing a variety of neurologic disorders, including ASD." (PMID 24355397, 2013). "This narrative review summarizes some of the most recent therapeutic approaches approved or under investigation for the treatment of SCN1A-, SCN2A- and SCN8A-related neurologic disorders." (PMID 41515912, 2025).
genetic disorders (11 papers, 2017 to 2026). "Sodium channelopathies are genetic disorders caused by pathogenic variants in the voltage-gated sodium channel gene family, such as the sodium voltage-gated channel alpha subunit 1 (SCN1A), SCN2A, SCN4A, and others." (PMID 39165469, 2024). "The most common genetic etiology is SCN1A, but other genetic disorders can present with the phenotype." (PMID 41890472, 2026). "Antisense nucleotides (ASO) therapy to increase mRNA of SCN1A for NaV1.1 channel expression in normal levels is a promising strategy for genetic disorders involving haploinsufficiency." (PMID 33013363, 2020).
movement disorder (9 papers, 2017 to 2025). Neurological conditions resulting in abnormal voluntary or involuntary movement, which may impact the speed, fluency, quality and ease of movement. "Myoclonus is the main type of movement disorder associated with CACNA1A (approximately 82.8%), KCNA2 (75%), SCN1A (approximately 61.5%), and SCN8A (60%) mutations." (PMID 40217411, 2025).
tumor (6 papers, 2009 to 2024). "According to the results, SCN4A/5A/8A were highly expressed in tumour tissues, while SCN1A/2A/7A/11A were expressed at low levels (p < 0.05)." (PMID 35126466, 2021). "The results of the UALCAN database had showed that SCN2A/4A/5A/8A mRNA were highly expressed in tumour tissues, while SCN1A/7A/11A mRNA were expressed at low levels (p < 0.05), furthermore, the expression of SCN4A and SCN7A had the similar levels in microarray analysis result." (PMID 35126466, 2021). "Interestingly the proton exchange transporter gene NHE1 (SLC9A1) that is important for tumour metastasis was down-regulated, as well as the sodium channel transporters SCN1A, SCNN1B and SCN7A." (PMID 19662092, 2009). "Overall, SCN1A mRNA expression level was significantly higher in non-tumoral samples compared to GBM tissue (non-tumor: 7.7 ± 0.2 log2, n = 10; GBM: 6.5 ± 1.2 log2, n = 538; p = 1.9E-03, Bonferroni correction)." (PMID 39251990, 2024).
infection (4 papers, 2012 to 2025). The state of being infected such as from the introduction of a foreign agent such as serum, vaccine, antigenic substance or organism. "Testing for SCN1A mutations will be necessary for those infants suspected to have DS in order to provide early management in terms of temperature and infection controls." (PMID 22848613, 2012).
psychiatric disorder (4 papers, 2012 to 2026). A disorder characterized by behavioral and/or psychological abnormalities, often accompanied by physical symptoms. "They suggested that SCN1A mutation may contribute to the expression of psychiatric disorders in addition to epileptic seizures and combined effect of different gene variants may determine the ultimate phenotype of patients." (PMID 22848613, 2012).
cancer (3 papers, 2019 to 2025). A tumor composed of atypical neoplastic, often pleomorphic cells that invade other tissues. "This tool was originally designed to predict the impact of cancer-inducing genes rather than membrane-expressed ion channels, and it too failed to differentiate between mild and severe SCN1A mutations." (PMID 30735520, 2019). "SCN1A has not been reported to be involved in cancer origin and progression." (PMID 36052170, 2022).
SCN1A also shares sentences with these, for which no sentence is quoted: migraine with aura (8 papers); Arrhythmia (7); familial febrile seizures (7); cognitive decline (6); brain disease (5); schizophrenia (5); cortical dysplasia (4); depression (4); arthrogryposis (3); heart failure (3); idiopathic generalized epilepsies (3); Long QT syndrome (3); ovarian carcinoma (3); Panayiotopoulos syndrome (3); Atrophy (2); behavioral disorders (2); Blindness (2); central nervous diseases (2); colorectal cancer (2); cystic fibrosis (2); dementia (2); Fever (2); genetic generalized epilepsy (2); Headache (2); irritable bowel syndrome (2); Jeavons syndrome (2); Lennox-Gastaut syndrome (2); Menkes disease (2); metabolic disorders (2); myoclonic-atonic seizures (2).
A further 137 diseases each share a sentence with SCN1A in 2 papers or fewer.